CDKN2A (cyclin dependent kinase inhibitor 2A)
Diseases named in the same sentence as CDKN2A in open-access papers (continued):
Sharing a sentence is not in itself a finding about the gene and the disease.
cancer (continued). "The clinical consequence and probable molecular processes of CDKN2A in various malignancies were also explored in this work, revealing the significant function of CDKN2A expression in pan-cancer and offering a fresh and potentially effective therapeutic target." (PMID 38206516, 2024). "The CDKN2A locus has been mentioned previously, but in the present context, it should be mentioned that, at the end of the last century, it was already known that the promoter of INK4A is hypermethylated in several cancers, favouring the alternative transcription of ARF." (PMID 38893242, 2024). "The complex regulatory responses of cancer cells to CDKN2A inactivation may account for the development of resistance in cancer cells to CDK4 inhibitors." (PMID 39351198, 2024). "We can consider developing targeted drugs against the CDKN2A gene, which could promote the development of cancer cells towards the ferroptosis pathway." (PMID 38612764, 2024). "This genetic variant is a well-known negative prognostic factor in cancer, yet there are no therapies that selectively target CDKN2A/MTAP-deleted tumours." (PMID 38755480, 2024). "CDKN2A is highly expressed in almost all cancer types, while MTF1 is lowly." (PMID 38573998, 2024). "While promoter methylation of CDKN2A can lead to its low expression level, this alone does not show an independent association with the prognosis of cancer." (PMID 39273409, 2024). "Then, we conducted a comprehensive CDKN2A gene profiling analysis across cancers in GEPIA." (PMID 38894777, 2024). "In contrast, CDKN2A showed elevated expression in cancer tissues." (PMID 39727962, 2024). "Importantly, the knockout of CDKN2A leads to increased sensitivity of cancer cells to copper-induced cytotoxicity." (PMID 39702350, 2024). "Therefore, further in-depth examination of combined therapy with ICIs and CDK4/6 inhibitors in pan-cancer patients with CDKN2A ALT will be necessary in future studies." (PMID 38822443, 2024). "We checked the significant germline mutations, the mutations which could cause effects on cancer development or progression, only very three gene mutations were detected, including RUNX1, CDKN2A, and ERCC5." (PMID 39105897, 2024). "This study illustrates the CDKN2A MUT and DEL were associated with a poor outcome across cancers." (PMID 38822443, 2024). "The resulting increased cancer risk reduces the therapeutic potential of Cdkn2a inhibition in contrast to senolytic treatment, which removes senescent cells and does not promote cancer development." (PMID 39234801, 2024).
cancer (continued). "Similar results were observed among pan-cancer patients with CDKN2A DEL and other ALT." (PMID 38822443, 2024). "By contrast, CDKN1A and CDKN2A encode p21Cip1 and p16Ink4a, respectively, which are potent cell-cycle inhibitors in MCL, whereas FHL1 has been revealed to induce G1 and G2/M cell-cycle arrest by activating CDKN1A in human cancers." (PMID 36675119, 2023). "Overall the genomic landscape was stable, with pathogenic or likely pathogenic alterations being identified in 51 cancer genes, with 9 (18%) of them showing alterations being recurrent across different samples (MYCN, CDKN2A/2B, CDK4, GLI1, AKT1, IGF2, MED12, NCOR2)." (PMID 37730754, 2023). "The CDKN2A gene is frequently inactivated in human cancers, including NSCLC." (PMID 36835617, 2023). "In all EBV-related cancers, CDKN2A (p16INK4A) promoter hypermethylation is described." (PMID 37249755, 2023). "Strong prognostic role of CDKN2A in most cancers were observed, except TGCT." (PMID 36961395, 2023). "The results revealed that CDKN2A acts as a robust cancer prognostic and immunotherapy biomarker." (PMID 36961395, 2023). "CBioPortal webtool was employed to mine the genomic alteration status of CDKN2A across cancers." (PMID 36961395, 2023). "In general, these results indicated that the high expression of CDKN2A is related to the immunologic activation of cancer and may provide some clues for further research on the function and role of CDKN2A in the occurrence and development of cancer." (PMID 36961395, 2023). "CDKN2A expression is variable and context-dependent in different cancers." (PMID 38188288, 2023). "We analyzed the correlation between CDKN2A and various immune factors in pan-cancer." (PMID 36961395, 2023). "CDKN2A is often regarded as a tumor suppressor gene; however, hypermethylated CDKN2A may be responsible for poor cancer prognosis." (PMID 37265472, 2023). "Cyclin-dependent kinase inhibitor 2A/B (CDKN2A/B) is an important regulator of cell growth regulation and apoptosis, while the absence of cell proliferation regulation and cell cycle regulation is crucial for the development and progression of cancer." (PMID 37314514, 2023). "Therefore, the genetic and epigenetic alterations of CDKN2A can be employed as an immunological and prognostic biomarker in a pan-cancer model." (PMID 37626750, 2023). "Almost all of TCGA cancers have a higher expression level of CDKN2A than normal tissues." (PMID 36961395, 2023). "However, as an anti-tumor factor, CDKN2A is up-regulated in various types of cancers (31 types of cancers)." (PMID 37857018, 2023). "Only NFE2L2, CDKN2A, and FBXW7 were rarely mutated in normal samples than cancer samples." (PMID 36991467, 2023). "Finally, specific inhibitors which correlated with CDKN2A expression in different cancer types were also screened by using Connectivity Map (CMap) tool." (PMID 36961395, 2023). "CDKN2A is known to be an important tumor suppressor gene in several cancer including LUAD." (PMID 36727489, 2023). "The results indicated that CCNA2, CCNB1, CDK1 and CDKN2A were expressed in cancer epithelial cells." (PMID 37265472, 2023). "Furthermore, we demonstrated the potential component of targeted CDKN2A in pan-cancer using data downloaded from the CMap dataset." (PMID 36961395, 2023). "CDKN2A/B co-deletion was seen in 21 (23.1%) brain metastases across multiple cancer types." (PMID 36915611, 2023). "The methylation rate of CDKN2A has been extensively studied in various types of cancer." (PMID 38067304, 2023). "TIMER2.0 was used to analyze the immune cell infiltration relevance with CDKN2A in pan-cancer." (PMID 36961395, 2023). "Besides, the expression of CDKN2A in normal human samples and cancer cell lines were also presented in our study." (PMID 36961395, 2023).
cancer (continued). "More generally, CDKN2A is considered a biomarker in human carcinogenesis, and its methylation is the major mechanism by which cells can acquire an advantage in progression, in most human cancers." (PMID 36982734, 2023). "We firstly assessed the expression levels of CDKN2A in pan-cancer based on TCGA and GTEx data." (PMID 36961395, 2023). "To further understand how CDKN2A could be a predictive biomarker for cancer patient prognosis, we performed the univariate Cox regression to investigate the prognosis of 32 TCGA cancer types." (PMID 36961395, 2023). "Notably, we characterized, for the first time, the 5.1 kb true CDR from the CDKN2A/P16INK4A promoter to intron-2 in >90% of cancers containing CDKN2A deletion." (PMID 36531022, 2022). "There are significant differences in the expression of CDKN2A in many cancers." (PMID 36060256, 2022). "In drug sensitivity analysis and immune checkpoint analysis, the results showed that CDKN2A, DLAT, PDHA1 and GLS were negatively associated with some or most drugs in the cancer therapeutic response portal database, and the expression of DLST was positively correlated." (PMID 36588699, 2022). "The driver function of the CDKN2A gene in cancer development is enigmatic." (PMID 36531022, 2022). "Notably, the specific HCGs shared by both cancer cell lines included CDKN2A, CDKN2B, and MTAP deletions on chromosome 9 and RRAS2 insertions on chromosome 11." (PMID 35570408, 2022). "CDKN2A has been proved to play an important function in various cancers." (PMID 36338763, 2022). "Individuals with PVs in the CDKN2A gene also tend to have an earlier onset of cancer." (PMID 35372037, 2022). "Methylation of RASSF1A, CDKN2A, and LINE-1 and GNAS mutation may be relevant to cancer development, IPMN subtypes, and cancer prognosis." (PMID 35013462, 2022). "For example, dCas9-Dnmt3a-based system has been used to increase DNA methylation for repressing the transcription of oncogenes CDKN2A (cyclin-dependent kinase inhibitor 2A) and BACH2 (BTB domain and CNC homolog 2) in cancer development associated with aberrant DNA methylation." (PMID 36109806, 2022). "CDKN2A is one of the crucial defenses against cancer development in several human cancers." (PMID 35205261, 2022). "For example, CDKN2A (encodes tumor suppressors p16INK4A and p14ARF) and CDKN2B genes (encodes tumor suppressors p16INK4A-p14ARF and p15INK, respectively) are commonly deleted, or its promoter is silenced by methylation in human cancers." (PMID 35328644, 2022). "SCND inactivates the CDKN2A gene in 273 human cancer cell lines according to the COSMIC dataset." (PMID 36531022, 2022). "In addition to the recommendation for genetic counseling, three variants likely associated with an autosomal dominant cancer disposition supported a treatment recommendation, twice for PARP inhibition (BRCA1, CHEK2) and once for CDK4/6 inhibition (CDKN2A)." (PMID 35918329, 2022).
cancer (continued). "Because the true CDKN2A CDR was observed in more than 90% of CDKN2A-deleted cancer samples and the P16-Light assay is highly reproducible and convenient, the quantitative P16-Light assay should be considered a viable assay for detecting CDKN2A SCNVs in clinical practice." (PMID 36531022, 2022). "Studies have found that the carcinogenic pathogenesis of HPV infection is viral proteins E6 and E7-induced overexpression of cyclin-dependent kinase inhibitor 2A (p16Ink4a), which plays a role in cancer promotion, followed by the induction of malignant cell proliferation and carcinogenesis." (PMID 36686820, 2022). "In CDKN2A, variations have been reported for most positions of the ANK motif, and the majority of these variations have been reported to be associated with some type of cancer." (PMID 35056738, 2022). "The 5.1 kb CDKN2A CDR was found in >90% of cancers containing CDKN2A deletion." (PMID 36531022, 2022). "A 5.1 kb base-resolution CDR could be identified in >90% of cancer samples with CDKN2A deletion by sequencing." (PMID 36531022, 2022). "Finally, we extended the NSCLC findings by demonstrating an association between CDKN2A deletion and survival in ICI-treated patients across multiple cancer types." (PMID 35739333, 2022). "Interstitial deletion/fusion is the main type of CDKN2A SCND, and the breaking/fusing coordinates for CDKN2A SCNDs in cancer genomes are diverse, which blocks the establishment of a feasible detection assay for CDKN2A SCND, although many efforts have been made." (PMID 36531022, 2022). "CDKN2A, known as P16, is a classical tumor inhibitor gene in various types of cancers." (PMID 34988109, 2021). "For example, promoter methylation of P16 (CDKN2A or Ink4a) may directly inactivate gene transcription and drive cancer metastasis." (PMID 33634306, 2021). "Based on these data, CDKN2A may be a promising prognostic biomarker with a potential molecular mechanism that affects survival outcomes in cancer patients." (PMID 35004697, 2021). "Although CDKN2A/p16 is a known tumor suppressor gene, CDKN2A hypermethylation might be a predictive factor for unfavorable prognosis of portion cancer." (PMID 34906147, 2021). "Previous studies have reported that regulation of TERT, KRAS, and CDKN2A could serve as potential therapeutic targets in multiple cancer types." (PMID 34442467, 2021). "Furthermore, alterations in the associated genes (CDK-1, CDK-4, CCNE1, CDKN2A, RBI, NCAPG, AURKA, and CCND2) were determined in five CRC studies (CRC, TCGA, Firehose, CRC, TCGA, Nature, CRC, Pan-Cancer, MSKCC and CPTAC-2)." (PMID 33732631, 2021). "CDKN2A has the potential to serve as a biomarker in various cancers." (PMID 35004697, 2021). "To explore whether CDKN2A SCND may also affect distant metastasis of other cancers, we further mined The Cancer Genome Atlas (TCGA) PanCancer SCNV datasets." (PMID 35004325, 2021).
cancer (continued). "Consistently in multiple TCGA cancer cohorts, patients whose tumors had homozygous co-deletion of CDKN2A/MTAP and those who had HD of either gene had significantly shorter survival, with no statistical difference observed in the overall survival (OS) time among these three groups." (PMID 34556668, 2021). "In addition, CDK4 inhibitor proteins, including p16INK4a (CDKN2A), are often inactivated in many cancers." (PMID 34930213, 2021). "In general, the expression of CDKN2A played a detrimental role across cancers." (PMID 35004697, 2021). "Enrichment analysis indicated that CDKN2A expression was involved in natural killer cell-mediated cytotoxicity pathways, antigen processing and presentation, olfactory transduction pathways, and regulation of the autophagy pathway in multiple cancers." (PMID 35004697, 2021). "In addition, recurrent breakpoints of SVs targeting cancer genes commonly occurred in frequently deleted regions, e.g., CDKN2A on 9p21.3, MAML2 and ATM on 11q21-22, RAD51B, and TRAF3 on 14q 24-32.3, CYLD and NLRC5 on 16q12.1-13." (PMID 34234122, 2021). "Similarly, the detailed results of CDKN2A expression across different cancer types are summarized in UALCAN database." (PMID 34405225, 2021). "Somatic copy number deletion (SCND) of CDKN2A gene is the most frequent event in cancer genomes." (PMID 35004325, 2021). "p16 gene, also known as CDKN2A, is frequently inactivated in human malignant neoplasms." (PMID 32556556, 2021). "Liquid biopsy test reported actionable alterations in ARID1A gene, rearranged during transfection (RET) gene fusions, epidermal growth factor receptor (EGFR) gene R776H mutation, breast cancer (BRCA) genes 1/2, and cyclin-dependent kinase inhibitor 2A (CDKN2A) gene mutations." (PMID 33608032, 2021). "In addition, germline CDKN2A mutations are associated with higher risk of pancreatic adenocarcinoma (PDAC), with some evidence for increased cancers at other sites." (PMID 33823155, 2021). "Effect of CDKN2A SCND by CRISPR/Cas9 on biological behaviors of cancer cells was also studied." (PMID 35004325, 2021). "CDKN2A as a biomarker can be applied to assess prognosis in cancers." (PMID 35004697, 2021). "To evaluate whether our system may be used to introduce DNA methylation at other unmethylated promoters, we focused on CDKN2A, the promoter of which is hypermethylated in various cancers." (PMID 36618443, 2021). "Our sub-stratification analyses using public TCGA datasets show that the relationship between CDKN2A deletion and cancer metastasis may be organ/tissue-specific." (PMID 35004325, 2021). "Our cancer genome analysis showed a specific genomic profile of sarcomatoid HCC, which were characterized by a high mutation rate in cell cycle genes particularly CDKN2A." (PMID 34331411, 2021). "Together, these integrated analyses suggested that CDKN2A had prognostic value in cancers." (PMID 35004697, 2021). "Finally, we also found that CDKN2A deletion negatively correlated with the expression of T-cell markers in many other cancer types." (PMID 33842347, 2021). "As we reported recently, P14ARF is co-inactivated in 92% of CDKN2A-deleted cancers." (PMID 35004325, 2021). "However, these CRC cells also contain mutations in other cancer related genes (HCT116: KRAS, PIK3CA, CTNNB1, BRCA2, CDKN2A etc.; SW480 or SW620: KRAS and APC etc.), which constitute a unique pathological context in every CRC cell." (PMID 32388500, 2020). "Mutations in the PKHD1 and CDKN2A genes are not known to be cancer drivers in GBM according to the TCGA." (PMID 32041307, 2020). "Immune histology showed that ICB also failed to induce senescence in Cdkn2a-deficient RT2-cancers as they displayed a Ki67+p16Ink4a−, pHP1γ−, H3K9me3−, SA-β-gal− phenotype." (PMID 32165639, 2020). "Deletion of CDKN2A made cancer cells more sensitive to a selective activity inhibitor of CDK4/CDK6." (PMID 32860670, 2020).